MAP2K2 (mitogen-activated protein kinase kinase 2)
Diseases named in the same sentence as MAP2K2 in open-access papers (continued):
Sharing a sentence is not in itself a finding about the gene and the disease.
tumor (54 papers, 2007 to 2025). "The TCGA records have revealed the MAP2K2 protein in association with 51 missense variants in 57 patients across 16 tumor types; all of these variants are rare, as each appears only twice at the most." (PMID 35215249, 2022). "To validate the in vivo roles of EIF3B and MAP2K2, we established subcutaneous xenograft tumor models in mice." (PMID 40691141, 2025). "MAP2K2-KO in tumor cells also results in significant overexpression of the immune checkpoint receptor ligand PDCD1LG2 (LFC: 0.2, Q: 0.01) and downregulation of the marker of cytotoxicity GNLY (LFC: −0.29, Q: 0.03)." (PMID 40081369, 2025). "Oxidative phosphorylation components (NDFs, COXs, TCIRG1, LHPP) and chemical carcinogenesis pathways involving reactive oxygen species (CYP1B1, GSTs, AKT2, IKBKB, MAPK3, MAP2K2) exacerbate DNA damage and promote tumour aggressiveness." (PMID 41007296, 2025). "Collectively, our findings suggest that MAP2K2 knockdown counteracts the tumor-promoting effects of EIF3B overexpression, reinforcing the importance of the EIF3B-MAP2K2 axis in regulating tumor growth." (PMID 40691141, 2025). "In patient #19, fifteen oncogenic mutations were CDX tumor-exclusive, affecting genes such as CDK8, COP1, and MAP2K2." (PMID 36980717, 2023). "Genetic analysis of the tumor was performed using a diagnostic biochip for the detection of somatic mutations in the BRAF, NRAS, KIT, GNAQ, GNA11, MAP2K1, and MAP2K2 genes, Sanger sequencing for searching germinal mutations in the CDKN2A gene." (PMID 30782194, 2019). "MAP2K2/5 were high expression in all tumor stages (P < .05)." (PMID 40587753, 2025). "Moreover, EIF3B overexpression accelerated tumor growth in xenograft models, which was rescued by MAP2K2 knockdown." (PMID 40691141, 2025). "Conversely, tumor size was markedly reduced in the MAP2K2-downregulated group." (PMID 40691141, 2025). "RAD21, BOP1, POLR2E, and PRKDC were mainly expressed in tumor cells, RIPK2 was mainly expressed in monocytes, MAP2K2 was mainly expressed in tumor cells and macrophages, NBN was mainly expressed in macrophages and monocytes, and GPX4 was mainly expressed in tumor cells and T cells." (PMID 36212155, 2022). "USP21-mediated de-ubiquitination and stabilization of MAP2K2 promotes tumor growth of HCC." (PMID 34621787, 2021). "In one model (BoC71) with four SR tumors, we found two acquired KRAS mutations (G12V & G12C in BoC71 C3 & C4, respectively) and one MAP2K2 (Q60P) mutation (BoC71C1), while the fourth tumor (BoC71 C6) did not reveal any alterations known to drive SR." (PMID 34271981, 2021). "Genetic analysis of tumor tissue was performed using a diagnostic biochip (EIMB RAS, Russia) for the detection of most common somatic mutations in the BRAF, NRAS, KIT, GNAQ, GNA11, MAP2K1, and MAP2K2 genes." (PMID 30782194, 2019). "Collectively, these data establish a linear signaling axis where EIF3B enhances ERK/MAPK signaling via MAP2K2-mediated MEK activation, thereby driving tumor cell proliferation." (PMID 40691141, 2025). "Indeed, CEBPB and EP300, along with genes related to the Mitogen-Activated Protein Kinase (MAPK) signaling cascade such as MAP3K1, MAP2K2, and MAP3K11 were significantly upregulated in RMC tumor cells following treatment with nivolumab plus ipilimumab." (PMID 41290625, 2025). "The upregulation of key regulatory genes in the MAPK pathway, such as MAP2K1, MAP2K2 and SHC1, in tumour cells positive for the three integrin receptors further supports the involvement of the integrin‐MAPK signalling pathway in the functional maintenance of the C0 subpopulation." (PMID 38279519, 2024). "Furthermore, key regulatory genes in the MAPK pathway, such as MAP2K1, MAP2K2 and SHC1, were upregulated in tumour cells positive for the three integrin receptors." (PMID 38279519, 2024).
tumor (continued). "In addition, copper can affect mitogen-activated protein kinase kinase 1 (MEK1) and mitogen-activated protein kinase kinase 2 (MEK2) and enhance their phosphorylation of ERK1 and ERK2 in a dose-dependent manner, further promoting tumor cell proliferation." (PMID 37427098, 2023). "For the two MAPK inhibitors (selumetinib and trametinib) no differential expression of their targets (MAP2K1 and MAP2K2) was observed between tumor and normal tissue." (PMID 34200770, 2021). "Indeed, significant down-regulation of MAPK3, MAP2K2, MAPKAPK3, ELK1 and up-regulation of the phosphatase DUSP1 was found in the reprogrammed tumours." (PMID 29662623, 2018). "The total fluorescence intensity served as a surrogate marker for tumor burden, revealing that EIF3B overexpression intensified fluorescence intensity compared to the negative control (NC), whereas MAP2K2 knockdown diminished it." (PMID 40691141, 2025).
infection (14 papers, 2012 to 2025). The state of being infected such as from the introduction of a foreign agent such as serum, vaccine, antigenic substance or organism. "In line with previous observations, the expression of kinases belonging to the ERK signaling cascade (MAPK1, MAPK3, MAP2K1, and MAP2K2) remained unaltered after infection, while the levels of some proteins involved in MAPK14/p38 signaling changed significantly." (PMID 36298696, 2022).
adenocarcinoma (2 papers, 2008 to 2021). A common cancer characterized by the presence of malignant glandular cells. "Activated MEK2, i.e., MAP2K2, could transform epithelial cells and induce high-grade adenocarcinomas in a mouse orthotopic transplantation model." (PMID 34745971, 2021).
neurodegenerative disease (2 papers, 2021 to 2025). A disorder of the central nervous system characterized by gradual and progressive loss of neural tissue and neurologic function. "MAP2K2 is required for autophagy-associated clearance of pathological proteins, including Aβ, in neurodegenerative diseases." (PMID 33417228, 2021).
cardiac disease (1 paper, 2023). "Patients with MAP2K1 variants have a lower frequency of cardiac disease than those with MAP2K2 (64%) and BRAF variants (72%)." (PMID 38136934, 2023).
MAP2K2 also shares sentences with these, for which no sentence is quoted: hepatocellular carcinoma (7 papers); metastatic melanoma (5); clear cell renal cell carcinoma (4); viral infection (4); Cognitive impairment (3); metastatic tumors (3); non-small cell lung carcinoma (3); acute myeloid leukaemia (2); astrocytoma (2); bacterial infection (2); breast adenocarcinoma (2); cardiomyopathy (2); gastric cancer (2); lung adenocarcinoma (2); lymphoma (2); neuroblastoma (2); papilloma (2); -dependent (1); anaplastic thyroid cancers (1); anemia (1); anthrax (1); Arthritis (1); autoimmune disease (1); bone marrow failure (1); brain tumor (1); breast tumors (1); cardiovascular disease (1); carotid atherosclerosis (1); CHARGE syndrome (1); cholesteatoma (1).
A further 61 diseases each share a sentence with MAP2K2 in 1 paper.